HR (HR lysine demethylase and nuclear receptor corepressor)
Diseases named in the same sentence as HR in open-access papers (continued):
Sharing a sentence is not in itself a finding about the gene and the disease.
breast cancer (continued). "Hormone receptor-positive (HR+)/human epidermal growth factor receptor 2-negative (HER2−) represents the most common molecular subtype of breast cancer." (PMID 40678728, 2025). "Multicenter data from 253 premenopausal patients with HR+/HER2+ early‐stage breast cancer who received trastuzumab from October 2009 to October 2018 were retrospectively included." (PMID 38185807, 2024). "Hormone receptor-positive (HR+)/HER2-negative (HER2-) breast cancer constitutes a considerable proportion of cases, and significant advancements have been made in its management." (PMID 38322413, 2024). "Chemotherapy combined with immunotherapy does present some challenges for patients with HR+/HER2- breast cancer." (PMID 39247184, 2024). "Another example is the recent analysis of HR+/HER2+ breast cancer patients from the phase III ShortHER study (n = 784), of which 40% (n = 309) were premenopausal." (PMID 38895891, 2024). "The PALOMA-2 trial confirmed that the combination of palbociclib and letrozole leads to significantly longer progression-free survival than letrozole alone in postmenopausal women with advanced breast cancer, i.e., HR+ and HER2-." (PMID 38344632, 2024). "Most breast cancer cases in the United States are hormone receptor–positive/human epidermal growth factor receptor 2–negative (HR+/HER2−), with higher percentages among male patients (78.3%–84.1%) versus female patients (66%–67.4%)." (PMID 37903899, 2024). "Abemaciclib can be used to treat postmenopausal women with breast cancer, with a clinical benefit rate of up to 72% for patients with HR+/HER2 breast cancers." (PMID 39464635, 2024). "Fourteen self-identified Black participants with HR+/HER2− advanced breast cancer completed the study, and their data was included in this analysis." (PMID 39184092, 2024). "Nevertheless, our trial was novel in that few studies have assessed dual checkpoint inhibition in the most common breast cancer subtype, HR+/HER2-negative, early-stage breast cancer." (PMID 38502947, 2024). "Nonetheless, the present study confirms that the probability of having ypT0 status of the breast is low in HR+/HER2+ breast cancer patients treated with neoadjuvant systemic treatment without chemotherapy." (PMID 39766087, 2024). "Of the 190 patients included with HR+/HER2+ breast cancer, 150 were treated with NET and 40 with NET+aHER2." (PMID 39766087, 2024). "Luminal B breast cancer is also HR+ and can be either HER2-positive (HER2+) or HER2-negative (HER2−)." (PMID 39767607, 2024). "The combination of palbociclib and tamoxifen provides value in expanding the treatment options for HR+/HER2− advanced breast cancer beyond palbociclib combinations with AI or fulvestrant." (PMID 39174547, 2024). "The trials will also be carefully analyzed for the risk of severe and/or long-term toxicity because most patients with HR+/HER2-negative early-stage breast cancer are cured with standard therapy." (PMID 38502947, 2024). "This study can guide clinicians and decision-makers regarding the best cost-effective use of CDK4/6 inhibitors in the first-line use of HR+/HER2- advanced breast cancer." (PMID 39114308, 2024). "From 2015 to 2022, 24 eligible patients were treated with CDK4/6 inhibitors for metastatic HR+/HER2- breast cancer." (PMID 38344632, 2024). "HR+/HER2- breast cancer is highly sensitive to hormone therapy, a property that makes endocrine therapy highly effective in these patients." (PMID 39247184, 2024). "This study followed a cohort of HR+/HER2-metastatic breast cancer patients who had previously been treated with AI and were subsequently given ET, with serial liquid biopsies collected throughout." (PMID 39684756, 2024). "The distinctive structural design of SKB264, coupled with its optimal balance between anti-tumor efficacy and safety, positions it as a promising candidate for targeting Trop-2 in breast cancer, specifically in HR+/HER2- patients." (PMID 39555080, 2024).
breast cancer (continued). "In the context of the widespread use of trastuzumab, the efficacy of OFS in premenopausal patients with HR+/HER2+ early‐stage breast cancer is still controversial." (PMID 38185807, 2024). "Among three major subtypes based on hormone receptor and epidermal growth factor receptor status, HR+/HER2- breast cancer is the most common subtype, accounting for one-third of all breast cancers." (PMID 38375194, 2024). "Taken together, these data indicate that HR+/HER2− breast cancer remains an area of interest for clinical evaluation of Aurora kinase combination therapies." (PMID 38672538, 2024). "The phase III MONALEESA-7 trial specifically focused on pre-/perimenopausal patients with HR+/HER2− advanced breast cancer and studied ribociclib plus endocrine therapy (ET) vs. placebo plus ET." (PMID 38339303, 2024). "Here we report results from the PATHWAY trial (NCCH1607), which has investigated the benefit of adding palbociclib to tamoxifen in patients with HR+/HER2− advanced breast cancer, in both pre-, peri-, and postmenopausal patients versus tamoxifen alone." (PMID 39174547, 2024). "The dose-expansion group included patients with HER3-high or HER3-low-expressing HR+/HER2- breast cancer, as well as those with HER3-high-expressing triple-negative breast cancer (TNBC)." (PMID 39456611, 2024). "We investigated the efficacy and safety of palbociclib–tamoxifen in patients with HR+/HER2− advanced breast cancer." (PMID 39174547, 2024). "Although HR+/HER2– breast cancer is highly endocrine responsive, resistance to endocrine therapy is common, and the risk of recurrence and death from breast cancer persists for over 20 years after original diagnosis." (PMID 39531335, 2024). "The confirmed objective response rate (ORR) was 26.8% in patients with HR+/HER2- breast cancer and 31.8% in those with triple-negative breast cancer (TNBC), indicating clinical activity." (PMID 39456611, 2024). "We conducted a retrospective review of 253 premenopausal patients with HR+/HER2+ early‐stage breast cancer treated with trastuzumab, and found that the addition of OFS had a significant benefit for the overall population." (PMID 38185807, 2024). "Of these, 207 patients had HR+ HER2− breast cancer and 181 patients had HER2+ breast cancer (n = 75) or TNBC (n = 106)." (PMID 38632652, 2024). "Mutations in the phosphatidylinositol-4,5-bisphosphate 3-kinase catalytic subunit alpha (PIK3CA) gene are present in approximately 40% of patients with HR+/HER2- breast cancer and are correlated with poor prognosis in advanced stages of the disease." (PMID 39555080, 2024). "In HR+/HER2- breast cancer, both T-DXd and HER3-DXd, ADCs directed against HER2 and HER3 respectively, have shown efficacy." (PMID 38992028, 2024). "Overall, 253 patients with HR+/HER2+ early‐stage breast cancer who received trastuzumab were included in the study." (PMID 38185807, 2024). "In part B, a total of 44 patients were assessed for eligibility, and 20 patients with HR+/HER2- breast cancer and 17 patients with TNBC were enrolled in the study to receive a single dose of 5.6 mg/kg HER3-DXd." (PMID 38992028, 2024). "The most common subtype of breast cancer is hormone receptor-positive/human epidermal growth factor receptor 2-negative (HR + /HER2−), accounting for 68% of cases." (PMID 38831191, 2024). "In SOLTI-1805 TOT-HER3 part A, 78 patients with HR+/HER2- breast cancer received a single dose of 6.4 mg/kg HER3-DXd." (PMID 38992028, 2024). "In conclusion, data from the PATHWAY trial showed the clinical benefit of treatment with palbociclib in combination with tamoxifen in patients with HR+/HER2− advanced breast cancer." (PMID 39174547, 2024). "The exception to this trend in the alisertib lead-in group was a patient with HR+/HER2− breast cancer with stable disease on treatment (A-2), for whom an increase in caspase to the highest level noted across both groups was observed after combination therapy." (PMID 38672538, 2024).
breast cancer (continued). "The combination of CDK4/6 inhibitors (CDK4/6i) with endocrine therapy (ET) has emerged as the foremost therapeutic modality for patients afflicted with hormone receptor-positive (HR + )/HER2-negative (HER2-) advanced breast cancer." (PMID 38409585, 2024). "SY-5609 commenced phase I clinical studies for the management of advanced solid tumors and in conjunction with Fulvestrant for women with HR+/HER2- breast cancer (ClinicalTrials.gov identification: NCT04247126)." (PMID 38983782, 2024). "Patients and methods: This retrospective multicenter study included elderly patients with metastatic HR+/HER2-negative breast cancer receiving first-line CDK4/6 inhibitors." (PMID 39456537, 2024). "Previously, mutations affecting the PIK3CA gene, which results in the hyperactivation of the alpha isoform (p110a) of PI3K, have been demonstrated in 28% to 46% of patients with HR+/(HER2−) advanced breast cancers." (PMID 38279318, 2024). "The use of Cyclin-Dependent kinase 4 and 6 (CDK4/6) inhibitors has profoundly changed the challenge of endocrine therapy (ET) resistance in hormone receptor-positive (HR+)/HER2-negative (HER2−) breast cancer." (PMID 38240835, 2024). "Testing is performed in over 50% of newly diagnosed HR + /HER2- breast cancer cases nationwide with this percentage rising, and as such more tumors with low-risk clinical features are undergoing ODX testing." (PMID 38879577, 2024). "The efficacy of OFS in premenopausal patients with HR+/HER2+ early‐stage breast cancer is still controversial." (PMID 38185807, 2024). "CDK 4/6 inhibitors have become a key drug in the clinical treatment of breast cancer and are often used in conjunction with ET, especially in patients with HR+/HER2-advanced or metastatic breast cancer." (PMID 39640578, 2024). "This research aims to optimize adjuvant ovarian function suppression (OFS) for premenopausal Indian women with hormone receptor-positive (HR+) /human epidermal growth factor receptor 2-negative (HER2-) early breast cancer (eBC)." (PMID 39867062, 2024). "Among patients with HR+/HER2− advanced breast cancer, palbociclib–tamoxifen resulted in significantly longer PFS than tamoxifen alone." (PMID 39174547, 2024). "The present study is a retrospective analysis of data from patients with metastatic HR+/HER2- breast cancer who were treated with CDK4/6 inhibitors at a tertiary care institute in Eastern India between 2015 and 2022." (PMID 38344632, 2024). "Hormone receptor-positive (HR+) breast cancer (BC) accounts for more than 65–70% of BC cases, and four fifths of these are HR+/HER2-negative (HER2−)." (PMID 38238761, 2024). "The breast cancer subtype was HR+/HER2− (luminal A) in 52.7% of patients, HR+/HER2+ (luminal B) in 11.2%, HR−/HER2+ (HER2 enriched) in 2.8% and HR−/HER2− (triple negative) in 2.7%." (PMID 36602294, 2023). "In HR + /HER2 + breast cancer patients, 91 (24.4%) of 373 AR positive achieved pCR, and the pCR rate was 26.8% (15/56) in AR negative patients (P = 0.769)." (PMID 37099044, 2023). "CDK4/6i combined with endocrine therapy is the standard of care for patients with HR + /HER2- advanced breast cancer." (PMID 38037159, 2023). "Pain, including bone pain and/or muscle and joint pain, was reported by 59% of participants with TNBC and 87% of those with HR+/HER2− breast cancer." (PMID 36649275, 2023). "In Module 2A, 31 patients with post-CDK4/6 inhibitor HR+/HER2− advanced breast cancer received samuraciclib in combination with fulvestrant: 6 at 240 mg OD and 25 at 360 mg OD of samuraciclib." (PMID 37488191, 2023). "We fervently expect that CDK4/6 inhibitors will expand their application to additional cancer types in addition to HR+/HER2− breast cancer." (PMID 37759823, 2023). "A total of 43 consecutive female patients with HR+/HER2- advanced breast cancer who received abemaciclib and endocrine therapy were retrospectively reviewed." (PMID 36902563, 2023).
breast cancer (continued). "Headaches/head pain was mentioned by 67% of participants with HR+/HER2– breast cancer (average bother rating 5.8) versus 24% of those with TNBC (average bother rating 5)." (PMID 36649275, 2023). "Aromatase inhibitors (AIs; e.g., letrozole, anastrozole, and exemestane), selective estrogen receptor modulators (e.g., fulvestrant), and selective estrogen receptor modulators (e.g., tamoxifen) have essential roles in the treatment of HR+/HER2− breast cancer." (PMID 37345147, 2023). "According to HR expression status, HER2+ breast cancer was divided into two subtypes, HR+/HER2+ and HR−/HER2+, with different prognoses." (PMID 37605516, 2023). "In our retrospective, real-world analysis, we observed a higher incidence of diarrhea in patients treated with abemaciclib and endocrine therapy for HR+/HER2- advanced breast cancer." (PMID 36902563, 2023). "Many new CDK4/6i and HER2-targeted medication combination schemes are now being investigated for treating both ER+/HER2+ and HR+/HER2+ breast cancer." (PMID 38293701, 2023). "This study cohort included 63 HR+/HER2- metastatic breast cancer patients who presented at the Peking University Cancer Hospital from December 2015 – March 2019 with metastatic relapse or de novo Stage IV metastatic disease." (PMID 37361577, 2023). "Approximately 60–65% of breast cancer cases are hormone receptor-positive (HR+) and human epidermal growth factor 2-negative (HER2−)." (PMID 37345147, 2023). "Among others, TME Stimulation has given rise to increased bone metastasis of HR+/HER2− breast cancer cells and enriched the presence of CSCs in the cell population." (PMID 37190183, 2023). "CDK4/6 inhibitors (CDK4/6i), such as palbociclib, ribociclib, and abemaciclib, have been approved by the FDA and have emerged as promising treatments for patients with HR + /HER2- breast cancer." (PMID 38037159, 2023). "Our studies of this combined stimulation have addressed the joint effects of factors of the hormonal, inflammatory and growth-promoting arms to act together and influence the pro-metastatic functions of HR+/HER2− breast cancer cells." (PMID 37190183, 2023). "Clinical trials studying the application of CDK4/6 inhibitors in ER+/HER2+ or HR+/HER2+breast cancer." (PMID 38293701, 2023). "In the current study, we have recapitulated the intricate nature of the TME by stimulating HR+/HER2− breast cancer cells with a selected complex of factors, representing the hormonal, inflammatory and growth stimulatory arms of the TME." (PMID 37190183, 2023). "Some studies have found that HER2+ breast cancer usually has higher levels of stromal tumor-infiltrating lymphocytes (TIL) than HR+/HER2– breast cancer, implying that HER2+ disease is usually more immunogenic." (PMID 36817926, 2023). "Vaginal dryness was mentioned by 87% of participants with HR+/HER2– breast cancer (average bother rating 6.5) and 35% of those with TNBC (average bother rating 6)." (PMID 36649275, 2023). "Here, we aimed to analyze the use of CDK4/6i and clinical outcome of patients with HR+/HER2− ABC at four certified German university breast cancer centers in clinical routine." (PMID 36876172, 2023). "Hormone-receptor-positive (HR+)/HER2-negative (HER2-) is the most common breast cancer subtype and accounts for more than 70% of all new diagnoses." (PMID 36902563, 2023). "Several symptoms were mentioned more frequently by participants with HR+/HER2– breast cancer than by participants with TNBC." (PMID 36649275, 2023).
breast cancer (continued). "More than three quarters of the participants had HR+/HER2- breast cancer subtype, 14.8%, HER2+, and 8.3%, triple negative." (PMID 38132022, 2023). "CDK4/6 inhibitors have changed the treatment strategy for HR+/HER2− advanced breast cancer patients, and more than 17 CDK4/6 inhibitors in combination with various drugs, are now being tested or have been tested in clinical trials." (PMID 35938171, 2022). "Currently developed combinatorial therapies have made remarkable progress in the efficacy of CDK4/6 inhibitors for HR+/HER2- metastatic breast cancer therapy." (PMID 35938171, 2022). "Many chemotherapeutic agents are used in the treatment of breast cancer, including Tamoxifen (ER-positive breast cancer), Pertuzumab (HER2-overexpressing breast cancer) and Voxtalisib (HR+/HER- advanced breast cancer) (Bhushan, Gonsalves & Menon, 2021)." (PMID 35875638, 2022). "A recent study estimating social costs due to work productivity loss, with ribociclib + endocrine therapy among premenopausal women with HR+/HER2- advanced breast cancer, has also been conducted from the Brazilian perspective." (PMID 36515302, 2022). "This is consistent with findings from an ongoing multicenter phase Ia FCN-437c monotherapy study in China that is enrolling women with HR+/HER2– advanced breast cancer (NCT04488107), as well as single-agent data reported for approved CDK4/6 inhibitors." (PMID 36291780, 2022). "Treatment with ribociclib can benefit premenopausal women, as well as all women with HR+/HER2- advanced breast cancer and in first and second lines of treatment." (PMID 36515302, 2022). "Since HR+/HER2− is the most common subtype of breast cancer and has the longest time to recurrence, there is an urgent need to find better prognosticators of metastatic outcome for this subtype." (PMID 35565297, 2022). "The lack of consensus on the prognostic relevance of HER2 overexpression mainly depends on the absence of randomized trials specifically addressing the benefits of EET in women with HR+/HER2+ breast cancers." (PMID 36387212, 2022). "Conclusion: 18F-FDG PET/MRI enables comprehensive high-quality radiomics analysis for the prediction of pCR in breast cancer patients, especially in those with HR+/HER2− receptor status." (PMID 35406499, 2022). "In the PALOMA-2 and PALOMA-3 clinical studies, palbociclib plus ET was effective compared with placebo plus ET in patients with HR + /HER2− advanced breast cancer." (PMID 33085032, 2021). "The migration of HR+/HER2+ breast cancer cells decreased at 24 h in the pyrotinib or SHR6390 groups compared with the control group, and the migration rate of pyrotinib combined with SHR6390 was significantly reduced after 24 h." (PMID 34977029, 2021). "Systemic and local treatments are addressed by three major breast cancer subtypes: HR+HER2−, HER2+, and TNBC." (PMID 34502492, 2021). "Among patients diagnosed with primary breast cancer, the majority (71–73%) of breast cancers are HR+/HER2‒." (PMID 34698970, 2021). "Considering the unique molecular patterns of breast cancer, specific molecular research on premenopausal patients with HR+/HER2− EBC is necessary." (PMID 34575612, 2021). "On 3 February 2015, the FDA granted accelerated approval of Palbociclib (in combination with letrozole) for postmenopausal women with advanced breast cancer, then in 2016 Palbociclib was approved for treatment of HR+/HER2− metastatic BC." (PMID 34946704, 2021). "NPV was highest in patients with HER2+ breast cancer and lowest in patients with HR+ /HER2− breast cancer." (PMID 34035335, 2021). "PRO data on patients with advanced breast cancer in the real-world setting are limited, especially in those with HR+/HER2− disease." (PMID 32894087, 2020). "Regarding the classifications of breast cancer subtypes, luminal A (HR+/HER2-) accounted for 71.09%." (PMID 33238981, 2020).